CTLA4 (cytotoxic T-lymphocyte associated protein 4)
Diseases named in the same sentence as CTLA4 in open-access papers (continued):
Sharing a sentence is not in itself a finding about the gene and the disease.
tumor (continued). "Finally, CTLA-4 expression was increased on all T-cell subsets found within the tumor, similar to PD-1 expression, but was expressed the highest on the Tregs as was observed with OX40 expression." (PMID 27195113, 2016). "Additionally, CTLA-4 antibody treatment enhanced effector T cell motility in the context of an anti-tumor response." (PMID 26870040, 2016). "Blockage of CTLA-4 would allow for activation of tumor-specific T cells." (PMID 28536390, 2016). "In conclusion, NPC patients with high tumor CTLA-4 expression had a poor prognosis." (PMID 26918337, 2016). "In the present study of NPC, CTLA-4 expression was found not only in TILs but also in tumor cells." (PMID 26918337, 2016). "Thus, FDA-approved antibodies blocking CTLA-4 and PD-1 and its ligand PD-L1 show promising anti-tumour effects in a wide range of tumour types by priming T cells against tumour antigens." (PMID 27782084, 2016). "CTLA-4 blockade can increase tumor-specific T cell activity by preventing T cell exhaustion." (PMID 28943622, 2015). "While CTLA-4 regulates early stages of T-cell activation, PD-1 limits the activity of T cells in peripheral tissues during inflammatory response and is therefore a major immune resistance mechanism in the tumor microenvironment." (PMID 26500646, 2015). "CTLA-4+ dots in tumor cell cytoplasm looked like transport vesicles." (PMID 25893809, 2015). "Tumor regression correlated with the CD8+/Treg ratio, suggesting that other forms of therapy that target Treg depletion might have a synergistic effect when combined with the tumor vaccine and CTLA-4 antibody molecules." (PMID 26236750, 2015). "A “triple threat” immunotherapy approach that includes OX40 stimulation may help augment the efficacy of dual PD-1/CTLA-4 blockade by enhancing the expansion, survival, and cytolytic activity of tumor-reactive effector T cells." (PMID 25763356, 2015). "Through whole genome and RNA sequencing (RNA-seq) of a SS patient's tumor we discovered a highly expressed gene fusion between CTLA4 (cytotoxic T lymphocyte antigen 4) and CD28 (cluster of differentiation 28), predicting a novel stimulatory molecule on the surface of tumor T cells." (PMID 25802883, 2015). "In the tumor microenvironment, CTLA-4 suppresses antitumor immune activities." (PMID 26161407, 2015). "Conversely, tumor infiltrating CD8 T cells had higher levels of CTLA-4 expression in α-PD-L1 mAb blockade treated mice, suggesting that tumor cells may be directly or indirectly using this pathway to suppress CTL-mediated killing." (PMID 25992292, 2015). "A comparison of three SBRT radiation regimens, 20 Gy × 1, 8 Gy × 3, and 6 Gy × 5, demonstrated marked differences between the single dose and the fractionated regimens in the ability to synergize with anti-CTLA-4 antibody treatment and induce an anti-tumor immune response." (PMID 26180685, 2015). "This suggests that resistance to CTLA-4 blockade could depend on other immunosuppressive mechanisms displayed by the tumor." (PMID 25859247, 2015). "Some studies have established partial correlations between outcomes with CTLA-4 blockade and peripheral-blood lymphocyte count, markers of T-cell activation, an “inflammatory” tumor microenvironment and maintenance of high-frequency T-cell receptor clonotypes precluding their utilization in clinics." (PMID 26439694, 2015). "PD-1 is now considered a better target than CTLA-4 because antibody-mediated blockade of PD-1 among tumor-infiltrating T cells within the tumor microenvironment leads to mitigated side effects and higher response rates, especially among patients with PD-L1 positive tumors." (PMID 26350600, 2015). "CTLA-4 blockade might not benefit patients in Groups 1 and 3 (those with CTLA-4low tumor cells) because of the scant levels of soluble CTLA-4 to neutralize." (PMID 25893809, 2015).
tumor (continued). "However, with regard to cancer treatment, the down-regulation of a tumor-specific T-cell response is an unwanted scenario, thus favoring an antagonistic CTLA-4 therapy." (PMID 26500646, 2015). "Interestingly, CTLA-4 levels and the percentages of tumor infiltrating CD4+Foxp3+ Tregs remained unchanged." (PMID 25851535, 2015). "Immune checkpoint blockade with monoclonal antibodies directed against CTLA-4, PD-1, and PD-L1 has shown striking anti-tumor activity in an increasing number of solid tumors and hematologic malignancies, including tumors previously not considered immune responsive." (PMID 26442214, 2015). "CTLA4 is expressed in tumour cells in different cancer types." (PMID 25505134, 2015). "Regarding the genotype distribution of the CTLA4 polymorphisms, no statistical differences for rs733618, rs4553808, rs5742909, or rs3087243 were found between patients with tumor and those without." (PMID 25667935, 2015). "Next, we determined whether checkpoint ligands for TIM-3, LAG-3 and CTLA4 were expressed on the tumor and cells within the tumor microenvironment (i.e., spleen)." (PMID 25614821, 2015). "Thus, the CD19-driven CD28 signal given in the absence of CD80 molecules is sufficient to trigger T-cell sustained proliferation and anti-tumor activity, which are unaffected by CTLA-4 inhibition." (PMID 26110267, 2015). "In particular, mouse tumor models demonstrate that blockade of the checkpoint protein, cytotoxic T lymphocyte antigen-4 (CTLA-4), a negative regulator of T cell responses, augments immunity to tumor cells when used on its own or in combination with other therapeutic interventions." (PMID 26079374, 2015). "Additional benefit may be gained with use of immune modulating adjuvants such as anti-PDL-1, anti-CTLA-4, GM-CSF, or IL-2 to overcome tolerance and optimize anti-tumor immunity." (PMID 25933160, 2015). "As TIL hypofunction has been associated with upregulation of surface inhibitory receptors, we wanted to study whether observed changes in tumor microenvironment also affect the expression of anergy/exhaustion markers CTLA-4 and PD-1 on CD8+ T-cells." (PMID 26107883, 2015). "Altering the balance between CD28/B7 positive and CTLA-4/B7 negative regulatory signals may enhance anti-tumor immune response." (PMID 25893809, 2015). "Hence, tumors with an endogenous anti-tumor immune response appear to be a better candidate for CTLA-4 blockade therapy." (PMID 26579545, 2015). "However, we also noted that some T-cells infiltrating the tumor exhibited the phenotype of exhausted T-cells (CTLA4+/LAG3+/TIM3+/IDO+)." (PMID 25940795, 2015). "However, since the bulk production of IFN-γ was increased, it appears that tumor-reactive CD8 T cells in anti-PD-L1/CTLA4 treated mice produce more cytokines on a per cell basis." (PMID 25614821, 2015). "In particular, degradation of FOXP3 may be the desired goal in tumor biology, to allow the propagation of antitumor responses, as has been demonstrated with anti-CTLA4 therapies." (PMID 26561546, 2015). "Here, we developed an experimental strategy to characterize the molecular networks that are operating within the tumor to mediate anti-CTLA4 induced tumor regression, and identify drugs that target these mechanisms and are able to increase therapeutic response rates." (PMID 26193793, 2015). "Interestingly, LRT resulted in an increase of tumor-infiltrating Tregs, while CTLA-4 blockade gave rise to reversal of Tregs in both tumors." (PMID 25980578, 2015). "Interestingly, combination of CTLA-4 blockade with a cellular vaccine transduced with granulocyte-macrophage colony-stimulating factor (GM-CSF) leads to significant tumor regression in low-immunogenic tumors." (PMID 26579545, 2015). "In this regard, it has recently been shown in mice that treatment with anti-CTLA-4 monoclonal antibodies might deplete Tregs in the tumor microenvironment." (PMID 25682197, 2015).
tumor (continued). "Interestingly, the stimulator of interferon genes (STING) pathway, which results in APC activation, production of IFN-β and priming of CD8 T cells against tumor antigens was shown to be critical for synergistic anti-tumor effects of anti PD-1 and anti-CTLA-4." (PMID 26580645, 2015). "Interestingly, even after tumor challenge, the expression levels of total CTLA-4 in CD44hiCD8+ T cells, and the percentages of CD4+Foxp3+ Tregs in lung tumors, spleens, or lymph nodes were not reduced in the immunized SKAP55−/− mice (Fig4F)." (PMID 25851535, 2015). "Furthermore, lenalidomide did not trigger proliferation (Q1) of CTL expressing immune checkpoint inhibitors CTLA-4 or PD-1 in response to the various HLA-A2+ tumor cells." (PMID 27668268, 2015). "Therefore, inhibiting CTLA-4 expression in 19z1-CD80+ T cells results in their enhanced anti-tumor efficiency." (PMID 26110267, 2015). "Notably, the frequencies of IFN-γ-producing tumor-reactive CD8 T cells from anti-PD-L1/CTLA4 treated mice were similar to those treated with the anti-PD-L1/LAG-3 and anti-PD-L1/TIM-3 combinations." (PMID 25614821, 2015). "Thus PD-1 predominantly regulates effector T cell activity within tissue and tumours, whereas CTLA-4 predominantly regulates T cell activation." (PMID 25823653, 2015). "Densityhigh patients had a survival advantage only if tumor CTLA-4 expression was low." (PMID 25893809, 2015). "Additionally, tumor-specific TIL function is enhanced at day 25 in dual treated mice in comparison to CTLA4 mAb alone, PD-L1 mAb alone, or mock treated mice." (PMID 25992292, 2015). "We therefore inferred that high density of CTLA-4+ lymphocytes indicates relatively strong immune function in the tumor microenvironment; in the present study, patients with densityhigh interstitial CTLA-4+ lymphocytes in their tumors understandably had better prognosis." (PMID 25893809, 2015). "As might be expected with blocking CTLA-4, the induction of a tolerance break against the tumor may be responsible for a variety of specific immune-related adverse events (irAEs) that occur in approximately 60 % of the patients treated by ipilimumab." (PMID 26337719, 2015). "In addition to its role in T cell priming, CTLA-4 also regulates the suppressive function of tumor-infiltrating Tregs." (PMID 26500653, 2015). "Early studies of antibody-mediated CTLA-4 blockade in a variety of transplantable tumor models (e.g., colon carcinoma, fibrosarcoma, ovarian cancer, and prostate cancer) demonstrated significant tumor response." (PMID 25941561, 2015). "While the clinical importance of immune checkpoints mediated by CTLA-4 and PD-1 has become clear, there are a number of other pathways active in the immune microenvironment that also appear to be important contributors to tumor immune evasion." (PMID 25941561, 2015). "Moreover, IFN-α2 and IL-2 increased the levels of activated tumor-infiltrating CD8+ T-cells concomitant with reduction in the CD8+ T-cell expression of anergy markers CTLA-4 and PD-1." (PMID 26107883, 2015). "However, high CTLA-4+ lymphocyte density was significantly correlated with good prognosis only when tumor CTLA-4 expression was low." (PMID 25893809, 2015). "The current study showed that CTLA-4 was expressed by tumor cells." (PMID 25893809, 2015). "First, anti-CTLA-4 treatment could improve the priming, then expansion of tumor-specific naive T cells." (PMID 26322044, 2015). "Due to the increased CTLA-4 expression observed on TILs after selection of α-PD-L1 resistant tumors, and increased CD80/86 expression on remaining tumor cells, we hypothesized that blockade of both CTLA-4 and PD-L1 might lead to better tumor control." (PMID 25992292, 2015). "First, a small trial showed that periodic infusions of anti-CTLA-4 antibodies after vaccination with irradiated, autologous tumor cells engineered to secrete GM-CSF (GVAX) generated clinically meaningful antitumor immunity in a majority of metastatic melanoma patients." (PMID 26217587, 2015).
tumor (continued). "CTLA-4 regulates T cell activity in the early stage predominantly, and PD-1 mainly limits the activity of T-cell in the tumor microenvironment at later stage of tumor growth." (PMID 26279307, 2015). "We also demonstrate that CTLA4-FasL confers a specific and highly effective killing of tumor cells of the B cell lineage, both in-vitro and in-vivo, indicating that CTLA4-FasL might have a possible role as a new anti-cancer agent." (PMID 25227919, 2014). "In this study, we aimed to develop a molecular imaging probe for CTLA-4 visualization in tumor." (PMID 25365349, 2014). "Furthermore, where treatment with RT failed to produce long-term survival, immunotherapy with anti-4-1BB and anti-CTLA-4 antibodies produced a long-term tumor free survival in 3 out of 18 mice (16.7%)." (PMID 25013914, 2014). "Tumor growth may be suppressed by either DNA vaccines against CTLA-4 or purified specific anti-CTLA-4 monoclonal antibody." (PMID 25265018, 2014). "Importantly, CTLA4-FasL efficiently inhibited the growth of human B cell lineage tumors in a xenograft model, by provoking tumor cells’ apoptosis." (PMID 25227919, 2014). "High CTLA-4 expression was confirmed in the CT26 tumor tissues of tumor-bearing BALB/c mice." (PMID 25365349, 2014). "This down-modulation of CTLA-4 may help explain the improved activity of tumor-specific T cells found in the current work, consistent with previous findings." (PMID 24982761, 2014). "The antibody has been shown to operate by reducing CTLA4-induced T cell inhibitory functions, but also by targeting activatory Fc receptor-expressing effector cells against CTLA4-expressing Tregs, thereby blocking their immunosuppressive functions in tumours." (PMID 24969320, 2014). "As blockade of CTLA-4 is known to abrogate the suppressive activity of Tregs and improves tumor immunity, the combination of anti-CTLA-4 mAb and anti-GITR mAb elicits a more potent antitumor response causing rejection of advanced stage tumors than does either mAb alone." (PMID 25386340, 2014). "Herein, the constitutive expression of CTLA-4 and PD-1 on Tregs may play a crucial role in inhibiting anti-tumor T-cell responses." (PMID 24822170, 2014). "Therefore, we assumed that the T cells were responsible for CTLA-4 expression in the CT26 tumor tissues." (PMID 25365349, 2014). "CTLA-4 is an inhibitory receptor also expressed by tumor-infiltrating T cells." (PMID 24829760, 2014). "From those reports, we hypothesized that CTLA-4 expression in the CT26 tumor tissues regulated by T cells." (PMID 25365349, 2014). "CTLA-4 was weakly expressed in the normal tissues surrounding the tumor." (PMID 25365349, 2014). "Anti-tumor immunity may be augmented by targeting negative regulators of T cell co-stimulation as evidenced by the development of anti-CTLA4 and anti-PD1 therapeutics, and may be extended to targeting Tregs and MDSCs." (PMID 24733360, 2014). "To determine if blockade of CD1d resulted in improved priming of anti-tumor CD8+ T cells in dLN of WT mice treated with local radiotherapy and anti-CTLA-4 mAb, we measured tumor antigen-specific production of IFNγ by dLN cells stimulated with a CD8 T cell epitope derived from the tumor antigen gp70." (PMID 25349699, 2014). "We have previously shown that the combination of local radiotherapy with anti-CTLA-4 induces a CD8+ T cell-mediated anti-tumor response effective at controlling the irradiated tumor as well as systemic metastases leading to increased survival of 4T1 tumor-bearing mice." (PMID 25349699, 2014). "These combinations have produced rapid and extensive tumor regression, which may exceed responses from CTLA-4 or PD-1/PD-L1 single-agent therapy based on preliminary observations." (PMID 26328216, 2014). "Both PD-1 and CTLA-4, which are expressed on activated T cell surfaces, inhibit tumoricidal effector T cell responses by engagement via specific ligands that are expressed on various tumor cells." (PMID 25105508, 2014).
tumor (continued). "In addition, CTLA-4 protein expression in the CT26 tumor was confirmed by immunohistochemical staining." (PMID 25365349, 2014). "Cytotoxic T lymphocyte-associated antigen-4 (CTLA-4), also known as cluster of differentiation 152 (CD152), is one of the most important molecules that are involved in the downregulation of the immune system and the anti-tumor response." (PMID 25365349, 2014). "However, ablation of a subpopulation of stromal cells (FAP+ cells) permitted immune control of tumor growth and uncovered the efficacy of immunotherapeutic antibodies (anti-CTLA-4 or anti-PD-L1), which resulted in acute tumor regression." (PMID 25538623, 2014). "However, the functional activity of tumor-specific T cells is likely to be attenuated by its receptor (CTLA-4 and PD-1) interactions with its ligands, which transfer negative regulation signals and ultimately prevent an effective antitumor immune response." (PMID 25202350, 2014). "Additionally, tumor-associated DCs also express various inhibitory molecules, such as programed death ligand-1 (PDL-1) and CTLA-4, which further contribute toward the silencing of anti-tumor T-cell response." (PMID 24782988, 2014). "To determine if blockade of CD1d in the context of radiotherapy and CD137 costimulation resulted in improved priming of anti-tumor CD8+ T cells in dLN of WT mice similar to that observed during anti-CTLA-4 blockade, we measured tumor antigen-specific production of IFNγ by dLN cells." (PMID 25349699, 2014). "Interestingly, we found that the expression of CTLA-4 as well as T cell markers was quite low in the CT26 tumor tissues from the BALB/c nude mice." (PMID 25365349, 2014). "We found significantly higher numbers of infiltrating CD4+ T cells in the brains of mice treated with the combination of anti-4-1BB and anti-CTLA-4 antibodies as well as the mice treated with triple therapy when compared to brains of non-tumor bearing mice (p<0.05)." (PMID 25013914, 2014). "One reason that could explain the reduced toxicity could be that the PD1/PD-L1 checkpoint interaction takes place peripherally, i.e., at the tumor site, whereas the CTLA4/B7 interaction occurs mostly centrally, i.e., in the lymphoid organs." (PMID 24594636, 2014). "Thus, a promising therapeutic option to achieve strong anti-tumor immune responses is the use of monoclonal antibodies against CTLA-4 and PD-1 alone or in combination." (PMID 24822170, 2014). "We were able to visualize CTLA-4-positive tumor by PET with 64Cu-DOTA-anti-CTLA-4 mAb as the probe." (PMID 25365349, 2014). "PDCD1 and CTLA4 are T cell surface molecules that can inhibit anti-tumor T cell responses." (PMID 24782321, 2014). "However, the combination of RT and anti-CTLA-4 induced significant tumor-specific IFNγ production (p < 0.005 versus all other groups), as expected given the therapeutic synergy we have previously shown with this combination." (PMID 25349699, 2014). "Despite the importance of CTLA-4 to autoimmunity and anti-tumor immunotherapy, the actual mechanisms responsible for its function are unknown." (PMID 25538704, 2014). "As a consequence, effects on tumor growth by Treg-targeting treatments such as anti-CTLA4 antibodies may also involve effects on NK cells." (PMID 25101668, 2014). "Other immunotherapies, such as antagonistic antibodies to the checkpoint inhibitor CTLA-4 and tumor vaccines, may also be enhanced by CR in aged host." (PMID 24682539, 2014). "Surprisingly, when CTLA-4 blockade was given in three dosages of 800 μg in a two-day interval – instead of the six day interval employed in our triple therapy protocol – the treatment was able to produce tumor free long-term survival." (PMID 25013914, 2014). "Furthermore, 64Cu-DOTA-anti-CTLA-4 mAb displayed significantly high accumulation in the CT26 tumor, thereby realizing non-invasive CTLA-4 visualization in the tumor." (PMID 25365349, 2014).